PPP1R1B (protein phosphatase 1 regulatory inhibitor subunit 1B)
Diseases named in the same sentence as PPP1R1B in open-access papers (continued):
Sharing a sentence is not in itself a finding about the gene and the disease.
tumor (22 papers, 2004 to 2025). "Low PPP1R1B mRNA expression was also linked to worse prognosis of patients with ER positive tumours, and CDC42 and GRB7, amongst others, were identified as PPP1R1B related genes using Artificial Neural Network (ANN) analysis." (PMID 38036593, 2023). "And this study revealed that extracellular vesicles derived from breast malignant cells can potentially stimulate the formation of new blood vessels by activating endothelial cells through transferring PPP1R1B in the tumor microenvironment." (PMID 37626402, 2023). "KCNQ1OT1 is up‐regulated in MTX‐resistant CRC tumour tissues and acts as the sponge of miR‐760, thus promoting the expression of the target gene PPP1R1B by activating the cAMP signalling pathway." (PMID 30997746, 2019). "Our experimental results and statistical analyses determined that lncRNA KCNQ1OT1 and PPP1R1B mRNA were aberrantly up‐regulated in MTX‐resistant CRC tumour tissues and cells." (PMID 30997746, 2019). "Taken together, our data suggest a more important role for Ppp1r1b in affecting tumor growth than metastasis per se, with t-Darpp apparently having the predominant role to play." (PMID 25128420, 2014). "We observed a median age of tumor initiation in PyMT/Ppp1r1b+/+ mice of around 15 weeks, with some mice reaching maximum tumor volume as early as 1–2 weeks later." (PMID 25128420, 2014). "We observed lower overall tumor volume in PyMT/Ppp1r1b-/- mice at 20 weeks of age and trends toward delayed tumor appearance in these mice as well." (PMID 25128420, 2014). "Nevertheless, our results with Ppp1r1b knockout mice are consistent with a role for t-Darpp in promoting tumor growth." (PMID 25128420, 2014). "Here, we explored the expression and function of PPP1R1B in tumor cell-derived sEVs." (PMID 37626402, 2023). "Once taken up by endothelial cells, PPP1R1B in turn promoted tumor angiogenesis and metastasis." (PMID 37626402, 2023). "The specific structure of blood vessels and the high expression of PPP1R1B in both tumor cells and endothelial cells may be responsible for the distant metastasis and progression of tumors." (PMID 37626402, 2023). "LncRNA KCNQ1OT1 and PPP1R1B mRNA were overexpressed in MTX‐resistant CRC tumour cells." (PMID 30997746, 2019). "A significant reduction in tumor volume, both in terms of total tumor volume (p = 0.023) and the volume of the largest tumor per mouse (p = 0.021), was observed in PyMT/Ppp1r1b-/- mice at 20 weeks, compared to PyMT/Ppp1r1b+/+ mice at the same time point." (PMID 25128420, 2014). "Looking at the effects of Ppp1r1b knockout in a slower growing tumor model, such as the MMTV-Neu model, might be helpful in elucidating the specific role of Ppp1r1b in both tumorigenesis and the processes associated with metastasis." (PMID 25128420, 2014). "Interestingly, this same mouse also had the largest total tumor volume among the PyMT/Ppp1r1b-/- cohort." (PMID 25128420, 2014). "Ppp1r1b knockout in MMTV-PyMT transgenic tumor mice resulted in a decrease in tumor growth." (PMID 25128420, 2014). "Accordingly, tumor cells were extracted for subpopulation analysis, and the identified malignant cells clustered into eleven subclones: BRCA_SRGN, BRCA_SLC39A6, BRCA_ITGB3, BRCA_PECAM1, BRCA_PPP1R1B, BRCA_VCAM1, BRCA_ICAM1, BRCA_S100A9, BRCA_GLUL, BRCA_TASTD2 and BRCA_AGR3." (PMID 37626402, 2023). "Larger tumor volume did seem to be roughly associated with a higher number of lung metastases, so it is not surprising that PyMT/Ppp1r1b-/- mice, with smaller primary tumors, on average, would also have fewer lung metastases than PyMT/Ppp1r1b+/+ mice." (PMID 25128420, 2014). "Also in TNBC, co-expression of DDR1 and Protein phosphatase 1 regulatory subunit 1B (PPP1R1B, also known as DARPP-32) inhibits tumor cell migration." (PMID 34805157, 2021). "No Darpp-32 or t-Darpp protein was detected in normal tissue from Ppp1r1b-/- mice (Ppp1r1b knockout in the absence of PyMT), nor tumor tissue from PyMT/Ppp1r1b-/- mice." (PMID 25128420, 2014).
adenocarcinoma (6 papers, 2009 to 2025). A common cancer characterized by the presence of malignant glandular cells. "The PPP1R1B locus also codes for t-Darpp, a transcriptional variant and amino-truncated isoform of Darpp-32 whose function within the PKA pathway is not known, but which is overexpressed in many adenocarcinomas and has been associated with drug resistance in cell lines." (PMID 19593441, 2009).
neurodegenerative disease (6 papers, 2019 to 2025). A disorder of the central nervous system characterized by gradual and progressive loss of neural tissue and neurologic function. "Combined with the expression levels in the brain and the supporting literature evidence related to neurodegenerative diseases in vivo and in vitro, we screened out FBXL20, PPP1R1B, NEUROD2 (NDF2), and ERBB2 (HER2) for follow-up molecular biology experiments." (PMID 35694256, 2022).
infection (4 papers, 2009 to 2025). The state of being infected such as from the introduction of a foreign agent such as serum, vaccine, antigenic substance or organism. "MA10 infection induced seven additional down-regulated (Hsp90aa1, Tcf7l2, Gnas, Sparcl1, Ywhag, Cpe, Sparc) and four upregulated DEGs (Ppp1r1b, Penk, Arpp21, Pcp4), whereas Aβ pathology resulted in five down-regulated (Cplx1, Syp, Meg3, Snhg11, Penk) and one upregulated DEG (Psen1)." (PMID 41497643, 2025).
movement disorder (3 papers, 2012 to 2021). Neurological conditions resulting in abnormal voluntary or involuntary movement, which may impact the speed, fluency, quality and ease of movement. "In a population with chronic mental illness, various SNPs in 10 candidate genes (PPP1R1B, BDNF, DRD3, DRD2, HTR2A, HTR2C, COMT, MnSOD, CYP1A2, and RGS2) reached nominally significant (p≤0.05) associations with drug-induced movement disorder." (PMID 22615781, 2012).
cardiac diseases (1 paper, 2020). "Thus, we speculate that together with MyoD, Ppp1r1b-lncRNA may play a role in cardiac diseases progression." (PMID 31953255, 2020).
PPP1R1B also shares sentences with these, for which no sentence is quoted: Parkinson disease (11 papers); breast tumor (10); Dyskinesia (9); psychiatric disorder (8); bipolar disorder (7); Anxiety (6); Parkinsonism (5); gastric adenocarcinoma (4); gastric tumor (4); lung adenocarcinoma (4); lung carcinoma (4); mood disorder (4); non-small cell lung carcinoma (4); Alzheimer disease (3); Cognitive impairment (3); Neurological Disease (3); R6 (3); Atrophy (2); Brain atrophy (2); cardiac hypertrophy (2); esophageal squamous cell carcinoma (2); glioblastoma (2); Hepatic fibrosis (2); invasive ductal carcinomas (2); small cell lung carcinoma (2); Stroke (2); acute myeloid leukemia (1); autism spectrum disorder (1); autosomal dominant inherited disorder (1); brain cancer (1).
A further 33 diseases each share a sentence with PPP1R1B in 1 paper.